TRIM25 (tripartite motif containing 25)
Diseases named in the same sentence as TRIM25 in open-access papers (continued):
Sharing a sentence is not in itself a finding about the gene and the disease.
HCMV infection (1 paper, 2020). "Following HCMV infection, TRIM25 knockdown resulted in significantly lower levels of ZAPS protein and RNA levels with a corresponding increase in ZAPL levels indicating a TRIM25 dependant change in differential splicing of ZAP." (PMID 32886716, 2020). "Finally, we show that TRIM25 regulates alternative splicing between the ZAP short and long isoforms during HCMV infection and interferon induction, with knockdown of TRIM25 resulting in decreased ZAPS and corresponding increased ZAPL expression." (PMID 32886716, 2020).
invasive breast carcinoma (1 paper, 2020). A carcinoma that infiltrates the breast parenchyma. "Probing the TCGA database, alterations in TRIM25 were observed in several cancer types, most notably amplifications in the invasive breast carcinoma (BRCA) and mesothelioma datasets." (PMID 33115448, 2020).
lentivirus infection (1 paper, 2020). Virus diseases caused by the Lentivirus genus. "Using lentivirus infection to express shRNA, we generated stable OTUD5 knockdown cells, into which the control siRNA or siRNA against TRIM25 was transfected." (PMID 32826889, 2020).
Listeria infection (1 paper, 2015). "We found that UBE1L (E1), UBE2L6 (E2), HERC5 and TRIM25 (E3s) mRNA are all significantly upregulated following Listeria infection, as is the deconjugating enzyme USP18." (PMID 26259872, 2015).
liver fibrosis (1 paper, 2025). "TRIM25 knockout mice exhibited significantly lower liver fibrosis levels compared to controls." (PMID 40231613, 2025).
measles (1 paper, 2023). A highly contagious viral infection caused by the measles virus. "Polymorphisms in TRIM25 have been reported to be associated with immune responses to measles vaccine." (PMID 37221558, 2023).
metastatic tumours (1 paper, 2021). "The expression of APP, on the other hand, decreases in both primary and metastatic tumours., We found TRIM25 to be indirectly targeted by all the compounds, except in MDA-MB-231 under indole-3-carbinol." (PMID 34193143, 2021).
Mycobacterium infection (1 paper, 2023). Infections with bacteria of the genus Mycobacterium. "Although the role of TRIM25 in parasitic infection has not been explored, its expression is reported to be enhanced during mycobacterium infection." (PMID 37761803, 2023).
neuropathy (1 paper, 2021). A disorder affecting the nervous system that manifests with pain, tingling, numbness, and/or muscle weakness. "It is unclear if TRIM25 is interacting with CLEC16A and affecting neuropathy in our Clec16aΔUBC mice." (PMID 33927318, 2021).
Obesity (1 paper, 2018). Accumulation of substantial excess body fat. "Next, we measured TRIM25 expression in adipose tissue from high-fat-diet (HFD)-induced obesity model mice and genetically induced obesity model mice (ob/ob)." (PMID 30323259, 2018). "In this study, we report a novel role of TRIM25 in regulating metabolic pathways by mediating PPARγ ubiquitination and its proteasome-dependent degradation, suggesting that TRIM25 may be a potential therapeutic target in PPARγ-mediated metabolic diseases such as obesity and type 2 diabetes." (PMID 30323259, 2018).
osteoporosis (1 paper, 2024). A condition of reduced bone mass, with decreased cortical thickness and a decrease in the number and size of the trabeculae of cancellous bone (but normal chemical composition), resulting in increased fracture incidence. "An ovariectomized mice model was established to evaluate the role of TRIM25 and exosomes in osteoporosis." (PMID 39563244, 2024). "Effects of BMSCs-derived Exos and TRIM25 on osteoporosis were further investigated in vivo in an OVX model study." (PMID 39563244, 2024). "To investigate the modulatory effect of BMSC-derived Exos on the progression of osteoporosis by regulating TRIM25, we conducted an in vivo study using OVX mice to mimic menopause-induced osteoporosis in women." (PMID 39563244, 2024). "However, the role of TRIM25 in osteoporosis has not been fully elucidated." (PMID 39563244, 2024).
Parkinsonism (1 paper, 2025). Characteristic neurologic anomaly resulting from degeneration of dopamine-generating cells in the substantia nigra, a region of the midbrain, characterized clinically by shaking, rigidity, slowness of movement and difficulty with walking and gait. "Meanwhile, a TRIM25 nonsense mutation (p.C168*) was found to be associated with autosomal dominant early-onset dementia and Parkinsonism, with biomarkers suggestive of AD." (PMID 40297993, 2025).
prostate tumors (1 paper, 2016). "Collectively, these results establish that TRIM25 is an ubiquitin ligase of full-length ERG as well as the N-terminally truncated ERG variants that originate from the TMPRSS2-ERG gene fusion in prostate tumors." (PMID 27626314, 2016). "Surprisingly, we found a positive correlation between the transcript levels of TRIM25 and ERG in ERG-positive prostate tumors in the RNA-seq data from The Cancer Genome Atlas (TCGA) consortium." (PMID 27626314, 2016).
renal carcinoma (1 paper, 2025). A carcinoma arising from the epithelium of the renal parenchyma or the renal pelvis. "MKRN2, ZNF598, UBE2D1, and TRIM25 were potential factors influencing renal cancer progression." (PMID 40959281, 2025).
renal cell carcinoma (1 paper, 2020). "To gather more evidence towards KLLN involvement in protein degradation, we used computational analysis of publicly available data from TCGA using the UALCAN web resource and observed that in renal cell carcinomas, KLLN, TRIM25 and MDM2 gene expression are positively correlated with each other." (PMID 33400740, 2020).
Sepsis (1 paper, 2021). Sepsis is defined as life-threatening organ dysfunction caused by a dysregulated host response to infection. "Our results give direction on how sepsis master regulators work coordinately in disease progression, especially MEF2A, TRIM25, and RFX2, with potential implications in pediatric sepsis prognosis." (PMID 34680414, 2021).
teratocarcinoma (1 paper, 2014). A germ cell tumor characterized by the presence of an embryonal carcinoma component and a teratoma component. "Using immunocytochemistry on mouse teratocarcinoma P19 cells, we found that Lin28a and Trim25 colocalize in vivo, supporting their functional link." (PMID 25457611, 2014). "To determine whether Trim25 plays a role in Lin28a-mediated uridylation, we performed Trim25 RNAi in mouse teratocarcinoma P19 cells." (PMID 25457611, 2014).
thyroid (1 paper, 2025). "documented that LncSLC26A4‐AS1 inhibits thyroid metastasis by promoting the binding of DDX5 and the E3 ligase TRIM25." (PMID 40490947, 2025).
thyroid cancer (1 paper, 2023). "SLC26A4-AS1 suppressed thyroid cancer metastasis by acting as a scaffold of DDX5 and TRIM25." (PMID 37582794, 2023).
viral encephalitis (1 paper, 2023). Encephalitis resulting from viral infection. "Li found that the ceRNA pathways of circ_0000220, miR-326-3p and BCL3/MK2/TRIM25 played roles in viral encephalitis, demonstrating that viral encephalitis caused by JEV infection is regulated by a complex ceRNA network." (PMID 38249464, 2023). "JEV infection of mouse brain tissue can cause significant changes in circRNA_0000220 and the downstream targets of circRNA_0000220, i.e., miR-326-3p and BCL3/MK2/TRIM25, ultimately affecting the occurrence of viral encephalitis." (PMID 38249464, 2023).
infection (75 papers, 2010 to 2026). The state of being infected such as from the introduction of a foreign agent such as serum, vaccine, antigenic substance or organism. "To test this, we assayed protein expression both before and after SINV infection and found that with the exception of the ZAPL ZnF mutants, protein expression for all ZAP and TRIM25 variants increases to varying degrees during infection." (PMID 35800389, 2022). "Interestingly, some replicates fail to initiate infection in the presence of TRIM25-WT, causing seemingly large variability in viral replication." (PMID 36067236, 2022). "Moreover, the upregulation of the tripartite motif-containing 25 (TRIM25) protein at the beginning of the infection may be associated with RIG-I in the detection of viral RNA intermediates." (PMID 31865850, 2020). "These experiments revealed the appearance of HMW, potentially ubiquitylated, TRIM25 species and a decrease in the lower-molecular weight (LMW) TRIM25 band over the course of infection." (PMID 40719442, 2025). "Quantification of total anti-TRIM25 immunoreactive bands in uninfected and infected cells showed a decrease in anti-TRIM25 levels over the course of infection." (PMID 40719442, 2025). "HMW TRIM25 proteins were evident as early as 1 hpi, persisted throughout infection, but were reduced at 24 hpi." (PMID 40719442, 2025). "We measured the amount of viral RNA at 18 h post infection (hpi) and found that deletion of TRIM25 increased SeV replication compared to wild-type HEK293T cells." (PMID 38750080, 2024). "Western blot results showed that CSFV in vitro infection of PK-15 and 3D4/2 cells for 24 and 48 h was able to obviously promote the protein expression of TRIM25." (PMID 38100396, 2024). "Upon infection, TRIM25-WT accumulated into cytoplasmic foci that co-localise with the viral RNA and are consistent with ROs." (PMID 39353916, 2024). "Our findings suggest that TRIM25 inhibits HEP-Flury infection by activating the RIG-I-mediated type-I IFN response." (PMID 37628607, 2023). "Interaction of NS1 with the host proteins PI3K and TRIM25 is paramount for NS1’s role in infection and pathogenesis by promoting viral replication through the inhibition of apoptosis and suppressing interferon production, respectively." (PMID 36769298, 2023). "To further investigate the role of the mechanism of TRIM25 regulating the RIG-I-IFN axis during HEP-Flury infection, we first confirmed that TRIM25 mediates RIG-I ubiquitination." (PMID 37628607, 2023). "This study found that infection with HEP-Flury upregulated the transcription level of TRIM25 mRNA nearly 2-fold, and the protein level of TRIM25 was significantly increased according to Western blot detection." (PMID 37628607, 2023). "Our study found that overexpression of TRIM25 during HEP-Flury infection induced upregulation of IFNα and IFNβ expression levels, thereby limiting viral replication." (PMID 37628607, 2023). "In the present study, we observed a strong upregulation of TRIM25 expression after HEP-Flury infection." (PMID 37628607, 2023). "In summary, in this study, TRIM25 is identified as a novel host resistance factor for HEP-Flury infection." (PMID 37628607, 2023). "HEK293T LacZ CRISPR-TIM1 cells were infected with concentrated trVLP supernatants in the absence of transfection of vRNP components, then fixed 4 to 6 hours post-infection and stained for NP and TRIM25." (PMID 35533151, 2022). "As expected, infection with TRIM25 and p85α significantly blunted the cardioprotective effects of TRIM25 against DOX-induced deterioration of cardiac function." (PMID 35871160, 2022). "Both TRIM25 and ZAP directly bind SINV RNA, and have been demonstrated to associate more strongly with SINV RNA during infection." (PMID 35800389, 2022).
infection (continued). "We characterized the ubiquitination of the most enriched TRIM25 interactors, G3BP and UPF1, as well as two TRIM25-R54P specific interactors during infection, NME1, and PABPC4." (PMID 36067236, 2022). "The first one interacts with the cellular polypeptide tripartite motif-containing protein 25 (Trim25), which regulates the host innate immune response to infection by ubiquitin ligases." (PMID 36146814, 2022). "In contrast, TRIM25 only gave a detectable NFkB-dependent signal at 48h (i.e. 24h after p1 cells infection)." (PMID 35533151, 2022). "In the previous study, tripartite motif-containing protein 25 (TRIM25) was significantly upregulated at 24 h post-infection (hpi) with DTMUV in DF-1 cells." (PMID 34595229, 2021). "Expression of TRIM25 by WT virus-infected cells increased markedly at 24 h post-infection, before falling rapidly at 28 h post-infection, whereas expression of TRIM25 in NS1mut-infected cells remained relatively stable during the course of infection." (PMID 34068322, 2021). "Collectively, these results indicate that TRIM25 is important for effective control of JCV replication and that, in turn, JCV tAg targets TRIM25 during infection." (PMID 33849980, 2021). "The relative mRNA expression of DTMUV significantly increased in two TRIM25 siRNA-transfected DEF lineages after DTMUV infection." (PMID 34595229, 2021). "In contrast, there was altered expression in aged lung on day 3 post infection, with increased Dhx58, Cyld, Trim25, and Ddx58 detectable in aged H1N1 infected lung tissue." (PMID 34829979, 2021). "In young lung, there was similar expression patterns in H1N1 and H3N2 lung, with increased expression of Ddx58, Trim25, and Dhx58 detected on day 3 and Cyld expression on day 5 post infection." (PMID 34829979, 2021). "Strikingly, in addition to increasing late viral protein expression, siRNA knockdown of TRIM25 results in a substantial reduction in ZAPS expression following infection with HCMV and a corresponding increase in ZAPL expression." (PMID 32886716, 2020). "The host-factors relevant for infection, such as TRIM25, seem to be a target for Dot1L modulation even in uninfected cells." (PMID 32188146, 2020). "We infected 293T with endogenous TRIM25 and ZAP expression with SINV, and immunoprecipitated TRIM25 to look for ZAP association at various time points following infection." (PMID 28060952, 2017). "We found that H9N2 (P < 0.01) and GPV (P < 0.001) infection significantly upregulated TRIM25 mRNA levels in the treated PBMCs." (PMID 27995135, 2016). "The mRNA levels of goose TRIM25 in the lungs were significantly upregulated on day 7 after infection." (PMID 27995135, 2016). "Infection of TRIM25 −/− cells with PR8 virus resulted in higher plaque forming units (PFU) as compared with WT MEF cells, underscoring the important role of TRIM25 for an efficient antiviral response in mouse." (PMID 23209422, 2012). "First, ectopic expression of TRIM25 triggered a significant inhibition of virus yields at 24 hrs post-infection (40%), as expected from its ability to restore IFN induction in Huh7.25/CD81 cells as shown in previous figures." (PMID 20485506, 2010). "Moreover, TRIM25 levels were found to decrease ~40% in a proteasome-dependent manner over the course of infection of HFFF-TERT cells with VACV-WR." (PMID 40719442, 2025). "We also examined whether infection of HeLa cells with other Orthopoxviruses promoted TRIM25 ubiquitylation." (PMID 40719442, 2025). "Interestingly, in Vero cells, milk supplementation reversed the infection-induced downregulation of TRIM25." (PMID 41157297, 2025). "Of note, a study using diGly enrichment to identify ubiquitylated proteins in mature CPXV-BR virions with a limited examination of cellular protein ubiquitylation during CPXV-BR infection of HeLa cells identified diGly peptides from TRIM25, as well as several other proteins identified in our study." (PMID 40719442, 2025).
infection (continued). "Infection of HeLa cells with viruses able to induce TRIM25 HMW species (VACV-Cop, CPXV-BR) also induced the formation of TRIM25 punctae, whereas those that could not induce TRIM25 HMW species (vP811, ECTV-Mos) did not." (PMID 40719442, 2025). "The results suggest that HEP-Flury infection increases the expression of TRIM25." (PMID 37628607, 2023). "Using next-generation sequencing, we found that TRIM25 is upregulated during HEP-Flury infection." (PMID 37628607, 2023). "We found that HEP-Flury infection significantly increased the mRNA and protein levels of TRIM25." (PMID 37628607, 2023). "Based on the observed expression level of TRIM25 after HEP-Flury infection, we speculated that TRIM25 may be a key factor in host response to HEP-Flury infection." (PMID 37628607, 2023). "Overall, TRIM25 expression was highly facilitated after infection both in vitro and in vivo." (PMID 37391858, 2023). "The focus of this study was to investigate the function of TRIM25 in HEP-Flury infection." (PMID 37628607, 2023). "We wanted to verify whether TRIM25-mediated expression of type-I IFN in HEP-Flury infection was dependent on RIG-I." (PMID 37628607, 2023). "Therefore, further studies are required to uncover the host factors by which TRIM25 potentiates RIG-I-mediated type-I IFN response in HEP-Flury infection." (PMID 37628607, 2023). "Taken together, our work identifies TRIM25 as a new host factor involved in HEP-Flury infection, which may be a potential target for the development of antiviral drugs against RABV." (PMID 37628607, 2023). "Furthermore, we found that TRIM25 regulates type-I interferon response by targeting retinoic acid-inducible gene I (RIG-I) during HEP-Flury infection." (PMID 37628607, 2023). "Similarly, upon infection of TRIM25 KO DF-1 cells with ARV, the expression of the muNS viral protein was enhanced with respect to the expression in the parental DF-1 cells." (PMID 36519174, 2022). "Interestingly, on the seventh day after infection, the TRIM25 protein in nasopharyngeal tissue decreased significantly, with only G3BP2 and N colocalizing." (PMID 36560452, 2022). "Similar to the replication competent SINV Toto1101/luc, infection with the replication-deficient SINV Toto1101/luc:ts6 generally results in higher expression of ZAP and TRIM25 variants, though the phenotype for a 6 hour infection is not as robust as a 24 hour infection." (PMID 35800389, 2022). "However, in the later stage of infection, the expression of TRIM25 decreased to below the normal level, which was different from that of G3BP2." (PMID 36560452, 2022). "Finally, NS1 is also able to suppress TRIM25 expression at a transcriptional level through up-regulation of Dot1L methyltransferase during infection." (PMID 34835115, 2021). "Interestingly, TRIM25 already displayed increased expression relative to loading control at 3 hr post infection." (PMID 26259872, 2015). "Thus, it would be interesting to probe if infection with ZAP-resistant alphaviruses may modulate ZAP’s ability to interact with TRIM25 or TRIM25’s ability to ubiquitinate its target proteins and mediate antiviral activity." (PMID 37112813, 2023). "Moreover, TRIM25 is a limiting factor for HEP-Flury infection." (PMID 37628607, 2023). "In view of the shared mechanism of action, interference with the recruitment of the viral enzymes to the 14-3-3/TRIM25 complex could provide a new strategy for potentiating the host innate immune response during the early phases of infection and virus reactivation." (PMID 32226432, 2020). "Studies have found that 14-3-3ε interacts with RIG-I following an acute infection and promotes the ubiquitination of RIG-I by TRIM25 to stabilize 14-3-3ε, TRIM25, and the RIG-I translocon." (PMID 40431746, 2025). "To test if this was true in VACV-Cop-infected HeLa cells, we treated cells before and after infection with the proteasome inhibitor, MG132, and TRIM25 levels were examined at 4 and 8 hpi." (PMID 40719442, 2025).